MMP2 (matrix metallopeptidase 2)
Diseases named in the same sentence as MMP2 in open-access papers (continued):
Sharing a sentence is not in itself a finding about the gene and the disease.
lung carcinoma (continued). "Our results indicate that the nuclear translocation of HDAC6 functionally inhibits the invasiveness of lung cancer cells that may occur through the inhibition of MMP2 expression." (PMID 26388610, 2015). "MMP2 is a more sensitive predictor of lung cancer progression, metastasis, and survival than MMP9." (PMID 26388610, 2015). "PGE2 treatment also increased MIG-7 protein, EMT, MMP-2 activity and invasion of lung cancer cells." (PMID 25004182, 2014). "In this in vitro study, the NM significantly inhibited secretion of u-PA and increased secretion of TIMP-2 in lung cancer cell lines A-549 and Calu-3, as well as decreased MMP-2 secretion in A-549 cells, suggesting its potential in modulating lung cancer invasion and metastasis." (PMID 23563849, 2013). "Furthermore, a previous study demonstrated significant correlation between NM inhibition of Matrigel invasion and NM modulation of the MMP-2 and -9 activity of the lung cancer and MM cell lines studied." (PMID 23563849, 2013). "Lung cancer, the most prevalent cancer worldwide and malignant mesothelioma are highly aggressive tumors that are characterized by high levels of matrix metalloproteinase (MMP)-2 and -9 secretion." (PMID 23563849, 2013). "Therefore, through various functions, MMP2 is closely tied to lung cancer progression, including angiogenesis and migration.We also found MMP2 protein expression in high-metastatic 95D was more than that of in low-metastatic 95C." (PMID 23936390, 2013). "Our findings indicate that POU5F1 is required for controlling cell invasion and migration via direct regulation of MMP-2 in lung cancer, and support the idea that POU5F1 and MMP-2 will be useful as potential biomarkers of prognosis and novel targets for lung caner therapy." (PMID 24386189, 2013). "Furthermore, GRN163L inhibited the migration/invasion of A549 lung cancer cells through the downregulation of MMP-2." (PMID 23545855, 2013). "However, when Gefitinib is used on lung cancer cells, integrin β1 and MMP2 function are up-regulated and leads to Gefitinib resistance." (PMID 23936390, 2013). "Our data indicate that both POU5F1 and MMP-2 may contribute to tumor initiation and invasion–metastasis phenotype of lung cancer." (PMID 24386189, 2013). "Strikingly, these cultures also express elevated Mmp10 mRNA, but no increase in Mmp2, Mmp7, Mmp9, Mmp11, Mmp12 or Mmp14, other Mmp species commonly linked to lung cancer." (PMID 22545096, 2012). "In this sense, the overexpression of MMP2, MMP9 and MMP3 has been detected in various types of human cancer, such oesophageal cancer, gastric carcinoma, ovarian and lung cancer, and has been significantly associated with tumour progression and decreased survival." (PMID 22455335, 2012). "SDC2 also suppresses MMP-2 activation, and subsequently metastasis, of lung carcinoma cells." (PMID 22900087, 2012). "FAK and MAPK signaling involved in MMP-2 secretion has been shown in QG90 lung cancer cells." (PMID 22454661, 2012). "Hence, the inhibition of MMP-2 in cancer cells appears to be an interesting therapeutic target of highly metastatic lung cancer cells." (PMID 23226337, 2012). "MMP-2, Twist and β-catenin play important roles in lung cancer metastasis." (PMID 20534110, 2010). "Another investigation found that FA could hinder the proliferation of H1299 cells, cell viability, and proliferation assay in vitro at a concentration of 0.06–0.6 μM of TFA in lung cancer by upregulating ROS, hydrogen peroxide, and superoxide anion and downregulating MMP2 and MMP9." (PMID 40487371, 2025). "Given the important role of SP in promoting inflammation and tumor progression, along with the critical involvement of MMP-9 and MMP-2 in cancer metastasis, we hypothesize that SP may promote lung cancer progression and metastasis through pathways involving MMP activity." (PMID 40321254, 2025).
lung carcinoma (continued). "Interestingly, MMP-2 expression did not exhibit a significant association with advanced lung cancer stages, brain metastases, or survival outcomes." (PMID 40321254, 2025). "We determine whether the modulation of hsa-miR-125b-5p and MMP-2 by S100A4-RAGE signaling in human lung cancer cells (A549) involves the activation of mitogen-activated protein kinases (MAPKs), including p38-MAPK, Jun kinase (JNK/SAPK), and extracellular signal-regulated kinase (ERK) pathways." (PMID 41155277, 2025). "Finally, assessing the clinical significance of hsa-miR-125b-5p and MMP-2 expression in lung cancer patients could help validate our results and pave the way for biomarker-based diagnostic and prognostic applications." (PMID 41155277, 2025). "Moreover, stimulation with TLR4 and TLR3 can induce the production of IL-6, CCL2/MCP-1, CCL20/MIP-3α, VEGFA (vascular endothelial growth factor A), and MMP2 known to play pivotal roles in the migration and invasion of lung cancer cells through induction of autophagy." (PMID 37443143, 2023). "Thus, it appears that MMP-2 plays a significant role in the development of lung cancer and might be used as a predictive marker of patient survival." (PMID 37509417, 2023). "Similarly, the results of siRNA experiments in lung cancer A549 cells suggested that MMP2 upregulates αVβ3 integrin mediated PI3K/protein kinase B (AKT) signaling to elevate vascular endothelial growth factor (VEGF) expression, resulting in enhanced angiogenesis." (PMID 36677584, 2023). "Thus, rhein may be a potential drug and the Stat3/Snail/MMP2/MMP9 pathway may represent novel potential targets for the treatment of lung cancer." (PMID 35178453, 2022). "Moreover, the MnPB NPs could inhibit lung cancer metastasis through downregulating the matrix metalloproteinase (MMP)-2 and MMP-9 expression in A549 cells." (PMID 35814022, 2022). "Thus, the inhibition of NF-κB suppresses MMP-2 and u-PA expression and lung cancer cell invasion." (PMID 34639167, 2021). "Similarly, more recent works demonstrated that metabolites of the flavonoid quercetin suppressed MMP-2 activity and invasion of a lung cancer cell line in a PPARγ-dependent manner, and that PPARγ blocked the increase in activities of MMP-2 and MMP-9 due to Toxoplasma Gondii infection in astrocytes." (PMID 34445581, 2021). "However, our results demonstrated that nano-EGCG might inhibit lung cancer cell invasion through an MMP-2- and MMP-9-independent pathway." (PMID 32198390, 2020). "Notably, nano-EGCG could suppress the invasion activity of lung cancer through MMP-2- and MMP-9-independent mechanisms; this differs from how EGCG was reported to exert effects on lung adenocarcinoma cells." (PMID 32198390, 2020). "Besides ceRNA, exosomal lnc-MMP2-2 can promote EMT by acting as an “enhancer- like lncRNA” and can bind to the upstream site of MMP-2 gene, resulting in augmentation of MMP2 expression in TGF-β- mediated lung cancer invasion and also increasing vascular permeability." (PMID 31575017, 2019). "Taken together, our studies showed that the high expression of HMGB1 in lung cancer, which may be used in the prognoses of lung cancer patients, promoted lung cancer invasion and metastasis by upregulating the expression and activity of MMP-2 via an NF-κB-dependent pathway." (PMID 29850505, 2018). "Collectively, these findings imply that inhalation of DP2 not only reinforces invasiveness of lung carcinoma cell via activation of integrin/FAK signaling but also may promote lung carcinoma metastasis via increasing production of tumor development mediators such as uPA, MMP-2, and IL-6." (PMID 28076322, 2017). "So far, more than 20 members of the MMP family were identified, among which MMP-2 has been extensively studied in human cancers and has been shown to be closely related to the invasive potential and metastasis of different types of tumor cells including lung cancer." (PMID 29113325, 2017).
lung carcinoma (continued). "Taken together, these results suggested that treatment with DBL may act as a potential candidate to inhibit lung cancer metastasis by inhibiting MMP-2 and -9 via affecting PI3K/AKT, MAPKs, FAK/paxillin, EMT/Snail and Slug, Nrf2/antioxidant enzymes, and NFκB signaling pathways." (PMID 28350337, 2017). "The overexpression of BTG2 may inhibit the growth and proliferation through inhibiting the protein expression of cyclin D1, and invasiveness through inhibiting the protein expression of MMP-1 (matrix metalloproteinase-1) and MMP-2 (matrix metalloproteinase-2) in the A549 human lung cancer cell line." (PMID 26132560, 2015). "The data presented here, indicated that knockdown of topoisomerase IIα and overexpression of JWA suppressed lung cancer cell migration and invasion abilities, which might be partially ascribed to elevated E-cadherin expression and decreased MMP-2/9, N- cadherin, ZEB1, slug and snail levels." (PMID 26046674, 2015). "Since MMP activity is required when cancer cells, including lung cancer, migrate and invade adjacent tissue, cells and extracellular matrices, we further investigated whether down-regulation of MMP2 transcription by miR-29c effects on MMP2 enzyme activity using gelatin zymography." (PMID 23936390, 2013). "For instance, Skp2 is reported to promote the invasion via enhancing the expression of MMP-2 and MMP-9 in lung cancer oral squamous cell carcinoma." (PMID 41385185, 2025). "TLR2 enhances lung cancer cell migration and invasion by promoting the expression of CCL2, IL-6, and MMP-2 through the cAMP-AMPK-TAK1 signaling axis." (PMID 41293166, 2025). "Specifically, CUR inhibits STAT3 phosphorylation and activation in lung cancer cells, leading to a 40%–60% reduction in tumor size and a significant decrease in the expression of STAT3 target genes such as cyclin D1, VEGF, MMP2, and MMP9." (PMID 40860906, 2025). "In contrast, miR-145-5p silencing upregulated MMP-2 and MMP-9 mRNA and protein levels, suggesting a key function of miR-145-5p in lung cancer cells through the regulation of MMP-2 and MMP-9." (PMID 40149594, 2025). "Another flavonoid, luteolin, inhibits lung cancer metastasis by decreasing TWIST1 and MMP2 expression." (PMID 39897041, 2025). "This study quantified SP abundance in lung cancer tissues and investigated its relationship with MMP-9 and MMP-2 expression, as well as its impact on clinical outcomes." (PMID 40321254, 2025). "In another study, TANs showed high secretion and activity of matrix metalloproteinase-2 (MMP-2) and MMP-9 under the endogenous interferon-beta (IFN-β) inhibition within the TME, demonstrating an N2-type TAN phenotype that promotes lung cancer development." (PMID 41023740, 2025). "A previous study reported that cisplatin and berberine inhibit the MMP-2 and MMP-9 pathways, reducing cell proliferation and inducing apoptosis in lung cancer." (PMID 40217305, 2025). "Firstly, hyperoside effectively inhibits the migration and invasion of A549 lung cancer cells by down-regulating the expression of metastasis-related genes, including MTA1, matrix metalloproteinase-2 (MMP-2), and its inhibitor TIMP-2." (PMID 40098612, 2025). "The data shown that MMP-2 and MMP-9 expression levels increase with advancing nodal stages, highlighting their crucial roles in lung cancer metastasis and progression." (PMID 39431222, 2024). "Our study's findings highlight silymarin's potential as a potent inhibitor of MMP-2 and MMP-9 in A549 lung cancer cells." (PMID 39431222, 2024). "Gelatin zymography assay indicates the silymarin has ability to inhibit the MMP-2 and MMP-9 expression in lung cancer." (PMID 39431222, 2024). "This analysis revealed significant differences in the expression of MMP-2 and MMP-9 between healthy individuals and those with lung cancer." (PMID 39431222, 2024).
lung carcinoma (continued). "Lung cancer patients exhibit abnormal TRPM7 expression, which activates the Hsp90α/uPA/MMP2 signaling pathway and induces pluripotent transcription factors, thereby enhancing the metastatic phenotype of lung cancer." (PMID 39633507, 2024). "PAR2 knockdown alone or treatment with gefitinib decreased MMP2 and MMP9 expression in lung cancer cells." (PMID 38172304, 2024). "Hyaluranon is known to stimulate expression of various MMPs including MMP2 and MMP9 in skin fibroblasts, keratinocytes, and lung cancer cells." (PMID 39018235, 2024). "Hyperglycemia induces MMP2 expression in cholangiocarcinoma by activating STAT335, upregulates MMP9 in lung cancer by inducing HMOX136, and upregulates MMP2/9 in breast cancer." (PMID 38200154, 2024). "TMEM196 overexpression suppressed the expression of MMP2, and of MMP7 in lung cancer cells, whereas TMEM196 knockdown had the opposite effect." (PMID 37367036, 2023). "TMEM48 knockdown showed decreased MMP-2 and MMP-9 expression in A549 and H1299 cells, indicating the role of TMEM48 in the invasion of lung cancer." (PMID 37367036, 2023). "We analyzed the association of the polymorphism frequencies of MMP-2-735C/T and MMP-9-1562C/T with MMP-2 and MMP-9 serum concentrations, as well as their potential effects in lung cancer patients." (PMID 37445754, 2023). "In lung cancer, indeed, SOX2 activates AKT/mTOR signaling pathway, which in turn enhances the activity of the matrix-metalloproteinase-2 (MMP2)." (PMID 38096163, 2023). "LMY1 self-assembles into nanofibers after being cleaved by matrix metalloproteinase-2 (MMP-2) and has the ability to target cancers that highly express MMP-2, such as lung cancer and CC." (PMID 38069380, 2023). "CUR (0, 15, 30, 45 and 60 μ mol/L) significantly inhibited lung cancer invasion and metastasis by inhibiting GLUT1/MT1‐MMP/MMP2 pathways and was also found to significantly inhibit GLUT1/MT1‐MMP/MMP2 expression and invasion in mice." (PMID 37697969, 2023). "Ouabain, a well-known cardiac glycoside, was reported to inhibit lung cancer cell migratory behavior by suppressing FAK activity and downregulating MMP-9 and MMP-2." (PMID 36362132, 2022). "Since HSP-90α can activate matrix metalloproteinase-2 (MMP2) and then accelerate maturation of MMP2 to induce tumor angiogenesis, invasion and development, HSP-90α protein become a biomarker to detect lung cancer and chemotherapeutic efficacy." (PMID 36417428, 2022). "In particular, MMP2 and MMP12 have been shown to degrade components of the ECM and correlate with lung cancer metastasis." (PMID 36241874, 2022). "In lewis lung cancer cells, overexpression of IDO enhanced Janus tyrosine kinase 2 (JAK-2) and STAT3 phosphorylation and up-regulated the production of Matrix metalloproteinase-2 (MMP-2) and MMP-9, two essential genes involved in invasion and metastasis." (PMID 35918736, 2022). "Naringenin (300 μM over a period of 24 h) decreased AKT and MMP-2 activities and inhibited migration of TSGH-8301 bladder cancer cells and proliferation of A549 lung cancer cells." (PMID 35884991, 2022). "Autophagy induced by TLR4 or TLR3 activation can enhance the production of cytokines such as IL-6, CCL2, MMP2, and CCL20 by promoting TRAF6 ubiquitination, thus facilitating the migration and invasion of lung cancer cells." (PMID 35422093, 2022). "Naringenin (100 and 200 μM, applied for 48 h) reduced the expression of MMP-2 and MMP-9, thus decreasing human lung cancer proliferation, migration and metastasis in vitro." (PMID 35884991, 2022). "An acidic microenvironment induces MMP2, MMP3, MMP9 and MMP13 expression to promote breast or lung cancer progression." (PMID 35414794, 2022). "Epigenetic regulation of Berberine-induced downregulation of HDAC expression and activity, indicated by a reduction in MMP-2 and MMP-9 mRNA and protein levels, also demonstrated suppression of the invasive and metastatic potential of A549 lung cancer cells." (PMID 36359829, 2022).
lung carcinoma (continued). "This showed significant migrastatic properties in three different cancer cell lines, lung cancer A549 cells, gastric cancer AGS cells, and colorectal cancer Caco2 cells, by modulating the expression levels of MMP-2/9." (PMID 35621924, 2022). "Our study agrees well with the reports related to the activity of selenite and SeNPs on decreasing pro-MMP-2/9 in HT1080 (fibrosarcoma) cells and the lung cancer cell line." (PMID 35957037, 2022). "Collectively, these data indicate that the interaction of CAFs with apoptotic lung cancer cells inhibits CAF migration and invasion via inhibition of TGF-β1 signaling pathways as well as MMP-2 and MMP-12 expression." (PMID 36241874, 2022). "Within humans, increased levels of MMP2 and TIMP2 were detected in the bronchial alveolar lavage fluid of 48 patients with various types of lung cancers." (PMID 36624735, 2022). "The results showed that the expression levels of MMP2 and NMIIA were significantly reduced in SFPQ knockdown NSC lung cancer-MSCs." (PMID 35707369, 2022). "We observed that luteolin reduced cell migration and the expression of pro-metastatic factors pro-matrix metalloproteinase (MMP)-2 and intercellular adhesion molecule (ICAM)-1 in PM2.5-exposed H460 lung cancer cells." (PMID 36185331, 2022). "Through dephosphorylation of Smad3 at the Thr179 site in A549 lung cancer cells, kaempferol inhibits the EMT, migration, and MMP-2 activation induced by TGF-1 in these cancer cells." (PMID 35986346, 2022). "In this study, the application of luteolin effectively reduces the expressions of PM2.5-induced pro-metastatic factors, such as pro-MMP-2 and ICAM-1, in human lung cancer H460 cells." (PMID 36185331, 2022). "A large number of scientific studies have shown that MMP2 and MMP9 are highly expressed in lung cancer tissues." (PMID 35814022, 2022). "Previous reports have demonstrated that TLR3/4 activation can increase the production of IL-6, CCL2, MMP2, and CCL20 cytokines by promoting TRAF6 ubiquitination and autophagy induction, thereby facilitating the migration and invasion of lung cancer cells." (PMID 35422093, 2022). "Herein, the effect of Smp24 on the viability, membrane disruption, cytoskeleton, migration and invasion, and MMP-2/-9 and TIMP-1/-2 expression of human lung cancer cells have been evaluated." (PMID 35878176, 2022). "We previously found that lnc-MMP2-2 is highly enriched in tumor growth factor (TGF)-β1-mediated exosomes and regulates the migration of lung cancer cells." (PMID 34285192, 2021). "Cell viability or apoptosis upon treatment with either MMP2 or MMP9 siRNA along with Aβ immunodepletion, showed that MMP2 is the predominant regulator of the cytotoxic effects induced by Aβ in lung cancer cells." (PMID 33958632, 2021). "Upregulated matrix metallopeptidase 2 (MMP‐2) and matrix metallopeptidase 9 (MMP‐9) promote migration of lung cancer cells." (PMID 33931980, 2021). "STAT3 curbs the RECK expression and increases the activity of MMP-2 and MMP-9 in lung cancer cells by up-regulation of miR-92a, promoting the malignant biological behavior of cells." (PMID 34790697, 2021). "Based on this evidence and our finding, the reduction in MMP-2 and MMP-9 expressions induced by ETD in lung cancer cells is a consequence of inactivation of Akt and its downstream effectors." (PMID 33758209, 2021). "Shen Kun-Hung found that solasodine (a natural glycoalkaloid) discouraged lung cancer metastasis by downexpressing miR-21 and MMP-2 (matrix metalloproteinase-2)." (PMID 33578944, 2021). "In lung cancer, SP1 participates in the induction of matrix metalloproteinase-2 (MMP-2) and matrix metalloproteinase-9 (MMP-9) to accelerate cell invasion." (PMID 34257529, 2021). "In this process, exosomal long noncoding-matrix metalloproteinase 2 (lnc-MMP2-2) RNA regulates the migration and invasion of lung cancer cells by enhancing MMP2 expression." (PMID 34281588, 2021).